MLANA (melan-A)
Diseases named in the same sentence as MLANA in open-access papers (continued):
Sharing a sentence is not in itself a finding about the gene and the disease.
melanoma (continued). "Haggerty and colleagues demonstrated that HSP90 inhibitors showed to upregulate the expression of tumor antigens such as Melan-A/MART-1, TPR-2, gp100 and enhance T cell recognition in melanoma cell lines." (PMID 33815422, 2021). "Melan-A and MELOE-1-specific T-cells were produced from HLA-A*0201 PBMC from melanoma patients, according to a validated procedure." (PMID 34120214, 2021). "In the group of naevi, the positivity rate for the conventional pan-melanoma cocktail was 43.18% (n = 19), respectively, 54.54% for HMB-45 (n = 24), 59.09% for tyrosinase (n = 26), and 84.09% for melan-A (n = 37), when examined individually." (PMID 33801642, 2021). "The majority of melanoma cell lines (23/40: 15/31 cutaneous, 8/9 uveal) showed features of the melanocytic state, including the high expression of MITF and Melan A along with low levels of AXL and/or NGFR." (PMID 34073253, 2021). "We analyzed expression of 3 melanoma antigens, gp100 (HMB-45), Melan-A (MART1) and Tyrosinase in skin biopsy samples from metastatic melanoma patients." (PMID 32231230, 2020). "The copy number of IL12RB2 was 1.5 times higher in the melanoma cell line versus the ‘normal’ melanocyte line, where the B16F0 cell line expressed over 330,000 copies of IL12RB2 and Melan-A cells had 214,000 copies." (PMID 32450888, 2020). "First, clinically relevant melanoma marker molecules PMEL and MLANA were detected in all cells and found significantly down-regulated in the YDFR-CB variant." (PMID 31892524, 2020). "Pathologists look for a melanoma cocktail antibody [most commonly S-100, human melanoma black (HMB)-45, Melan-A, and microphthalmia transcription factor (MITF)]." (PMID 33585548, 2020). "These were first reported in melanoma in which proteins (e.g., tyrosinase, Melan-A/MART-1, gp100/Pmel17) involved in melanin production or melanosome generation were often observed to be targets for CTLs from melanoma patients and healthy donors." (PMID 32585818, 2020). "Differentiation of PD from melanoma in situ mainly depends on immunohistochemistry, where S-100, HMB45, and Melan-A positive proteins can be identified." (PMID 33371071, 2020). "Most of the melanomas showing strong nuclear DLC1 were MELAN A positive (19/29; 65.5%), whereas a small portion of MELAN A+ cells exhibited weak nuclear DLC1 (10/29; 34.5%)." (PMID 32214200, 2020). "S-100 is a highly sensitive marker for melanoma; HBM-45, melan-A, MITF and tyrosinase are highly specific markers for this entity." (PMID 32724562, 2020). "Next, we tested if the 36 active compounds from the IFNγ HTRF assay and the cell viability assay can affect expression of genes that regulate melanoma cells differentiation and pigmentation such as MITF, DCT, Melan-A and Tyrosinase-related protein 1(Tyrp)." (PMID 32231230, 2020). "Immunomarkers, such as chromogranian and synaptophysin, Melan A and HMB45 or desmin and smooth muscle actin, are applied to differentiate neuroendocrine, melanoma and smooth muscle tumors, respectively." (PMID 32867094, 2020). "Here, we investigated the effect of Melan-A peptide and adjuvant CpG-B doses on the binding and functional avidity of vaccine-induced antigen-specific CD8 T-cells from melanoma patients after multiple monthly vaccine injections." (PMID 31969886, 2019). "Melanoma cells stain for melanocytic immunohistochemical markers such as HMB45, Melan-A, and S100 protein." (PMID 31699107, 2019). "Consistent with the loss of MHC-I expression, we also showed that the number of tumor-infiltrating CD8+ cytotoxic T lymphocytes dropped, in parallel with the reduced melanoma MHC-I and melan-A levels." (PMID 31426515, 2019). "The primary melanoma tissue revealed typical features of a melanoma including expression of S100, HMB45, and Melan A. Likewise, the metastatic brain tissue clearly showed melanoma-specific markers." (PMID 30858407, 2019).
melanoma (continued). "MLANA and its regulator MITF play a fundamental role in melanocyte development, tumor progression and are overexpressed in melanoma cells." (PMID 31681332, 2019). "Dacryocystectomyrevealed diffuse infiltration with large epithelioid cells, sometimes withpigments, which were positive for cocktail mix of antibodies to tyrosinase,melan A (MART-1), and HMB45, leading to pathological diagnosis of melanoma." (PMID 31747798, 2019). "Though mEHT promoted the release of damage-associated molecular pattern (DAMP) damage signaling molecules hsp70, HMGB1 and ATP to potentiate the tumor immunogenicity of melanoma allografts, it reduced MHC-I and melan-A levels in tumor cells." (PMID 31426515, 2019). "This study also showed the interest of evaluating MLANA and MIF expression in circulating melanoma cells in order to identify early stage patients with more aggressive disease." (PMID 31013837, 2019). "We found that SA-4 cells also express several genes typical of melanomas, such as MITF, MLANA, S100B, and TYR, which are otherwise poorly expressed in our panel of liposarcoma cell lines." (PMID 29570692, 2018). "CCSLT-GT shares its immunoprofile with malignant melanoma in case of S100 positivity but completely lacks HMB-45 and melan A immunoreactivity." (PMID 30636233, 2018). "In melanoma skin metastases, MYSM1 expression was consistently detectable in the majority of tumor cell nuclei as confirmed by double-staining for MYSM1 and Melan-A." (PMID 28978033, 2017). "Transcripts of MLANA, TYR, MAGEA3, PAX3, and ABCB5 were successfully identified from a single melanoma cell, as reflected by the increase in reciprocal Ct values (1/Ct)." (PMID 28978038, 2017). "The three melanoma markers (HMB-45, Melan-A, and S100) were expressed at similar relative levels in patient tumors and their corresponding xenograft tumors." (PMID 28645290, 2017). "Our case was S100 positive and negative for cytokeratins (excluding spindle cell carcinoma), smooth muscle markers (desmin, myogenin, and smooth muscle actin, excluding a smooth muscle tumour), and melanoma markers (HMB45 and Melan A)." (PMID 27672465, 2016). "The majority of corresponding primary melanoma tumors expressed strongly and diffusely PS100 and Melan A." (PMID 26945789, 2016). "In the Results section we describe the outcomes of three different experimental techniques for identifying different melanoma cell lines using S100, HMB-45, and Melan-A." (PMID 27087056, 2016). "Confirmatory immunostaining was demonstrating immunoreactivity for some or all of melanoma markers, such as S100, HMB-45, Melan-A and micropthalmia transcription factor (MITF), can be used to aid the diagnosis of metastatic melanoma." (PMID 27906105, 2016). "In the case of melanoma, specific melanoma antigens are incorporated (MART1/Melan-A, gp100, tyrosinase), which should be potentially recognized by cytotoxic T lymphocytes." (PMID 27998306, 2016). "It has been shown that Interferon-γ (IFN-γ) represses the expression of Melan-A, Tyrosinase–related protein 1 (TRP-1) and gp100 in melanoma cells and that this repression reduced recognition of these cells by specific anti-Melan-A CTL." (PMID 25853464, 2015). "Presence of melanoma markers as S-100, HMB-45, Melan-A, and PNL-2 must therefore be demonstrated through immunohistochemical staining to confirm the diagnosis." (PMID 24995141, 2014). "Further, prospective studies measuring circulating melanoma cells in 230 patients with melanoma and 152 healthy controls identified two other potential prognostic serological CTC markers; MLANA, a melanocyte marker, and ABCB5, a stem-like cell marker." (PMID 27429260, 2014). "Among these genes, the transcription factor MITF, the pigmentation enzyme TYR, and MLANA and GPR143 that are involved in melanosome biogenesis, are important players in melanoma." (PMID 25207815, 2014).
melanoma (continued). "Stainings with H&E and antibodies against the highly characterized melanoma markers S100B, HMB-45A and Melan-A revealed the highly cellular growth pattern of melanoma, and resemblance to the tumor biopsies from patients was observed." (PMID 25228592, 2014). "qRT-PCR analysis showed expression of melanoma differentiation markers MLANA, TYR and MITF in the panel of 54 melanoma cell lines." (PMID 25051363, 2014). "A histological melanoma is confirmed by the Fontana-Masson silver stain and the appropriate immunohistochemical staining pattern that includes HMB-45 antibodies, Melan-A, tyrosinase, and antimicrophthalmia transcription factor." (PMID 25642350, 2014). "Based on a screen for agents that enhance T cell recognition of Melan-A/MART-1, the iHsp90 17-Allylamino-17-demethoxygeldanamycin (17-AAG) was recognized as a potent stimulus of melanoma antigen expression." (PMID 25503774, 2014). "Together with Melan-A, immunostaining of HMB-45 and S100 increases the sensitivity and specificity for melanomas." (PMID 23533832, 2013). "Nevertheless, it should be noted that several known MITF target genes such as MLANA, RAB27a or SLC24A5 were weakly but significantly downregulated in all three melanoma cells, in accordance with the observations of a reduced MITF expression." (PMID 24344100, 2013). "The authors encapsulated the Melan-A peptide, which is a TAA from melanoma, in an influenza virosome and introduced the Melan-A peptide into plasmacytoid DCs (PDCs)." (PMID 24369016, 2013). "Using these pre-defined colorimetric settings, three melanoma TMA glass slides, digitalized independently, were analyzed with regard to the deconvolved H-CHANNEL and Melan-A-CHANNEL intensity variation." (PMID 23690928, 2013). "Anti-tumor immune response targets tumor-associated antigens such as cancer testis antigens (e.g., NY-ESO-1 or MAGEs) expressed by several tumors or differentiation antigens (e.g., Melan-A/MART-1, gp100, or tyrosinase) expressed in melanoma cells." (PMID 23801991, 2013). "However, this cell line also revealed specific expression of the melanoma markers tyrosinase and melan A. The authors hypothesized that the MDA-MB-435 cells exhibited lineage instability and classified them as a breast epithelial cell line that had undergone lineage infidelity." (PMID 23599796, 2013). "The S100 was not expressed in one case; therefore, we advocate concurrent use of other melanoma markers (HMB-45, Melan- A)." (PMID 24349741, 2013). "Identifying areas showing possible melanin pigment and immunostains with specific markers for melanoma, such as HMB45, Melan-A and S-100 protein, are diagnostically important." (PMID 22735126, 2012). "CCS and malignant melanoma share overlapping immunohistochemistry with regard to the melanocytic markers HMB45, S100, and Melan-A." (PMID 23170958, 2012). "The fish pigment cell tumors showed for several established melanoma markers expression profiles comparable to mammalian melanoma, for instance high expression of MART1/MLANA, and upregulation of N-cadherin with simultaneous downregulation of E-cadherin." (PMID 22693581, 2012). "Approximately one-third of melanoma patients had elevated MIF and MLANA transcripts (p<0.0001 and p<0.001, respectively) compared with healthy controls." (PMID 22829910, 2012). "With the MLANA and MIF targets, elevated levels were observed in a number of melanoma patients compared with healthy controls." (PMID 22829910, 2012). "Here, CTCs were enriched (∼400X) from blood of melanoma patients using a simple centrifugation device (OncoQuick), and 4 melanocyte target RNAs (TYR, MLANA, MITF, and MIF) were quantified using QPCR." (PMID 22829910, 2012). "Both MLANA and MIF were significantly higher in melanoma patients (p<0.013 and p<0.0001, respectively)." (PMID 22829910, 2012). "Clear cell sarcoma (CCS) and malignant melanoma share overlapping immunohistochemistry with regard to the melanocytic markers HMB45, S100, and Melan-A." (PMID 23170958, 2012).
melanoma (continued). "Immunohistochemistry staining showed malignant melanoma express S100, HMB-45 and Melan-A, but PBL don’t express these markers." (PMID 22568892, 2012). "Immunohistochemical staining revealed strong, diffuse positive staining for S-100 protein and positive staining for the melanoma markers HMB45 and Melan-A." (PMID 21722390, 2011). "Similar to their adherent counterparts, both Mela1 and SLM8 (data not shown) spheroid cells stain positively for at least one of the frequently tested melanoma markers HMB-45, MART1/Melan A and/or tyrosinase." (PMID 21526207, 2011). "Among 142 upregulated genes in melanoma, many are known to be expressed specifically in melanocytes, including KIT, Melan-A, TYR, TRPM1, EDNRB, DCT, SOX10 and SILV." (PMID 21294715, 2011). "The recurrent motif was found in Melan-A-specific CTL isolated from PBL and from tumor sites of HLA-A2+ melanoma patients, independently of the stage of disease and of the methodological approaches used for T-cell cloning." (PMID 19317896, 2009). "Typically melanoma is reactive for vimentin, S-100 protein, HMB-45, melan -A, tyrosinase, and microphthalmia transcription factor." (PMID 17910749, 2007). "Thus, we comparatively explored the expression not only of Melan-A/MART-1 and gp100 but also of tyrosinase genes, encoding differentiation antigens widely used in active specific immunotherapy in HBL and D10 melanoma cells cultured in either MCTS or conventional 2D conditions." (PMID 17342088, 2007). "In our previous study, the 'MCW Melanoma Cocktail'- a mixture of monoclonal antibodies- MART-1 {1:500}, Melan- A {1:100}, and Tyrosinase {1:50} demonstrated a highly discriminatory immunostaining pattern." (PMID 15500702, 2004). "This goal was completed using a comparison of CMC numbers, including their pre- and post-treatment status, evaluation of PMEL and Melan-A marker expression, and assessment of serum levels of S100B and TIMP-1 proteins in representative blood samples from melanoma patients and healthy controls." (PMID 40535809, 2025). "Additional ancillary markers such as Melan-A and SOX10 are sensitive for melanocytic differentiation and can help confirm melanocytic lineage; however, they do not distinguish between benign melanocytic proliferations (e.g., nodal nevi) and malignant melanoma." (PMID 40984891, 2025). "Furthermore, we have assessed the expression of the PMEL and Melan-A markers and the S100B and TIMP-1 protein levels in representative blood samples from melanoma patients and healthy controls." (PMID 40535809, 2025). "Immunohistochemical studies showed diffusely positive SOX10, Melan-A, HMB-45, preferentially expressed antigen in melanoma (PRAME) and patchy S100 immunoreactivity and were negative for p63 and GATA3, supporting the diagnosis of melanoma." (PMID 39363663, 2025). "MGNET typically shows positivity for S100 and SOX10 while being negative for melanocytic markers like HMB-45, Melan-A, and MiTF, which are usually present in melanoma and CCS." (PMID 40429661, 2025). "However, melanoma cells and normal melanocytes share common antigens (MART-1/Melan A, gp100, tyrosinase-related protein 1, 2)." (PMID 40861456, 2025). "Protein expression levels of known melanoma markers, such as MITF, MLANA, PMEL, TYR, and SOX10, had the lowest expression in EC-Mit samples (ANOVA, FDR < 6 × 10−4) and had a significantly lower expression in the EC-like subtypes when compared to the Mit-like subtypes." (PMID 40075679, 2025). "Desmoplastic melanomas are generally negative for Melan-A, with positivity reported in up to 27.3% of cases." (PMID 40507250, 2025). "The atypical cells were immuniohistochemically positive for HMB45 and Melan-A and negative for cytokeratins, consistent with malignant melanoma." (PMID 39402168, 2025). "Melanoma often exhibits marked nuclear pleomorphism and is positive for Melan A, HMB45, and Sox10—all negative in our case." (PMID 41409361, 2025).
melanoma (continued). "In this case, the absence of Hutchinson's sign and negative immunohistochemical staining for melanocytic markers, including Melan-A and SOX-10, helped exclude melanoma as a diagnosis, while the triangular sign and solitary lesions on nails were suggestive of malignancy." (PMID 41589154, 2025). "Another limitation is that MART-1/Melan-A staining was performed only on the specimen diagnosed as melanoma, and not on the initial moderate DN specimen for comparison." (PMID 40290790, 2025). "Common IHC markers used in melanoma diagnosis include S100, SOX10, Melan-A, and HMB-45." (PMID 40868240, 2025). "□ Melanoma: Common markers include S-100 protein, SOX-10, Melan A, HMB45, tyrosinase, and MITF." (PMID 40308487, 2025). "We analyzed PRAME and Melan A expression regarding the nuclear PRAME expression pattern and pagetoid spread of melanocytes by immunohistochemical staining in SSM with prominent nests, nested melanoma, and dysplastic melanocytic nevi." (PMID 40941765, 2025). "In this case, negative results for CD20 and CD3 excluded lymphoma, whereas melanoma was ruled out by negative results of Melan A and HMB‐45." (PMID 39802371, 2025). "Also, MELAN A and HMB45 were used for the lesions suspected to be melanoma and S100 staining for suspected neurological lesions." (PMID 39420710, 2024). "Therefore, we also explored any signs of melanoma progression in the 3D models by performing immunohistochemical staining for IDO-1 and Melan-A." (PMID 39062529, 2024). "The loading of Melan-A in EVs-VSV was validated by western blot and we confirmed that EVs-VSV contained higher quantities of Melan-A compared with EVs from uninfected melanoma cells." (PMID 39492948, 2024). "While Melan-A is more sensitive than HMB-45, both exhibit high specificity for melanoma." (PMID 39006602, 2024). "Further, our findings suggest an absence of typical melanoma markers, with the majority showing negative expression of S100 (n = 7) and melan A (n = 1), which is consistent with previously reported studies." (PMID 39199675, 2024). "While S-100 is the most sensitive marker for melanoma (sensitivity 97%-100%, specificity 75%-87%), HMB-45 and Melan-A provide good specificity (HMB-45 sensitivity 69%-93%, Melan-A sensitivity 95%-100% and specificity 75%-92%), though their sensitivity is lower." (PMID 39712693, 2024). "While S100 protein and SOX10 are typically positive in both MCNH and melanoma, the absence of other melanocytic markers, such as Melan-A and HMB-45, can support a diagnosis of MCNH." (PMID 39421096, 2024). "The authors concluded that immunohistochemical staining for the melanoma markers S100, HMB45, and Melan-A/Mart-1 enhances the sensitivity of the SLNB tenfold, allowing for the detection of one melanoma cell in one hundred thousand compared with one in ten thousand cells with routine stains." (PMID 36836846, 2023). "Pre-treatment of the NF-1LOF melanoma cell line MeWo and the BRAFMut MaMel51 with the RSK inhibitor PMD-026 could significantly enhance the activation of both gp100- and Melan-A-specific T cells as quantified by an increased IFNγ secretion." (PMID 37464364, 2023). "UM cells are commonly stained with melanocytic differentiation markers such as S-100, human melanoma black 45 (HMB45), melan-A/melanoma antigen recognized by T cells 1 (MART-1), melanocyte-inducing transcription factor (MITF) and sex-determining region Y-box 10 (SOX10)." (PMID 36765733, 2023). "MAAs (Pmel-17/gp100 and MART‐1/Melan-A) are proteins specifically expressed by melanoma cells, not normal cells." (PMID 37292567, 2023). "Some studies have reported that specific T-cell-recognized membrane proteins (Melan-A) have also demonstrated high sensitivity (about 93%) and specificity (about 99%) in differentiating non-melanocytic cells from melanoma, especially for primary tumors." (PMID 37292567, 2023). "There is evidence that Melan-A has high sensitivity and specificity in differentiating melanoma from non-melanocytic tumors." (PMID 37427124, 2023).